BRAF (B-Raf proto-oncogene, serine/threonine kinase)
Diseases named in the same sentence as BRAF in open-access papers (continued):
Sharing a sentence is not in itself a finding about the gene and the disease.
tumor (continued). "In addition to their direct effects on tumour cells through blockade of the MAPK pathway, BRAF/MEKi have also been shown to modulate the TME." (PMID 35366166, 2022). "In summary, when disease control is the treatment goal, most experts suggest that the primary tumor location should be considered, and anti-EGFR shows better treatment outcomes in left-sided RAS/BRAF WT mCRC because1L treatment is based on current clinical evidence." (PMID 34868987, 2021). "In addition, our data on the Fusobacteria relationship with the tumor molecular characteristics of MSI and KRAS/NRAS/BRAF status were consistent with studies using frozen tissue specimens and another study with FFPE tissue specimens." (PMID 34650531, 2021). "RSK4 demethylation restores its tumour inhibition to some extent, and RSK4 inhibitors combined with BRAF inhibitors may be a new strategy for tumour therapy." (PMID 34923978, 2021). "First, as local control with stereotactic radiosurgery (SRS) is better for smaller than larger tumors, the ability of combined BRAF and MEK inhibition to reduce tumor size in most patients may augment the efficacy of SRS." (PMID 34859235, 2021). "SM0014 (AM), whose tumor demonstrated a BRAF fusion, harbored evidence of both MAPK and PI3K pathway activation based on multiple phosphorylation events (BRAF S445, MEK1/2 S217/221, ERK1/2 T202/Y204, GSK3a/b S21/9, p70S6 kinase S371, P70S6 kinase T389, Akt T308)." (PMID 33826614, 2021). "Importantly, the mutant BRAF-targeting PROTACs described here mostly spare WT RAF, thus widening the potential therapeutic window of this new class of anti-tumor drugs." (PMID 33568647, 2021). "Indeed, sorafenib inhibits the phosphorylation of various targets present in the signaling pathways of both tumor cells (i.e., CRAF, BRAF, V600E BRAF, c-KIT, and FLT-3) and in the tumor-endothelial cells (i.e., CRAF, VEGFR-2, VEGFR-3, and PDGFR-β)." (PMID 34681219, 2021). "Primary tumor tissue genotyping resulted KRAS G12S and BRAF V600E mutated, respectively, whereas no RAS neither BRAF mutations were detected by cfDNA analysis." (PMID 34680277, 2021). "Consistently, dPCR assay detected the presence of BRAF (T1799A) only in DNA from the tumor tissue but not from the adjacent healthy tissue." (PMID 34613404, 2021). "In the RAS and BRAF wildtype cohort, the treatment arms were well balanced, apart from the primary tumour location in the PICCOLO trial, in which case the proportion of right-sided tumours was higher in the control (irinotecan) arm." (PMID 34253874, 2021). "There is some evidence that patients with RAS and BRAF wildtype mesenchymal CMS4 tumours may only benefit when anti-EGFR is combined with irinotecan, even in right-sided primary tumours." (PMID 34253874, 2021). "A prognostic biomarker (HER2; BRAF V600E mu­tations; RET gene rearrangements; high-level MET amplification) is indicative of patient survival independent of the treatment received because the biomarker is an indicator of the innate tumor aggressiveness." (PMID 34660150, 2021). "Ablation of BRAF in RAS-driven tumours did not result in a hyperactivation of ROK-α, indicating that both RAF isoforms play different roles in RAS mutant tumours." (PMID 33920182, 2021). "Among tumor suppressor lncRNAs are CASC15-S, Uc.283+A, and BRAF-activated lncRNA." (PMID 34575588, 2021). "Another similar study showed that regardless of the mutation prevalence, BRAF, and NRAS mutations are not necessary for melano-cytic tumor development." (PMID 34567185, 2021). "Further, we did not collect data on molecular abnormalities in primary tumour, e.g. the presence of activating mutations in the KRAS, NRAS and BRAF, or microsatellite instability and defective DNA mismatch repair (dMMR)." (PMID 33971834, 2021).
tumor (continued). "Plasma detected and tumor sample absent variants were also observed in two other patients, harboring one KRAS and one BRAF mutation, respectively." (PMID 34217228, 2021). "For univariate analyses, besides BRAF non-V600 mutations, other factors positively impacted on survival: age < 65 years, ECOG PS of 0, low tumor burden, absence of lung metastases and low tumor grading." (PMID 33925278, 2021). "However, SMAD4 gene mutation has no connection with other clinicopathology parameters, including patient age, gender, tumor grade, MSI status and BRAF status." (PMID 34301194, 2021). "From a therapeutic perspective, BRAF or MEK inhibitors may be effective, as they reduce tumor size and proliferation." (PMID 34441278, 2021). "Building upon previous studies showing synergistic activity of BRAF-MEKi with ACT, we investigated whether the addition of CDK4/6i could further improve anti-tumor responses." (PMID 34944961, 2021). "In the present study, of 60 PTCs, 41 were BRAF-mutated (68.3%) and TERT promoter-mutated (3.5%), in contrast to no NRAS or KRAS mutation in the tumor tissues." (PMID 33915745, 2021). "Positive mutation status was accompanied by an increase in NF-κB p65, NF-κBp50, VEGF HIF-2 VHL level compared to the primary tumor with negative BRAF-V600E status." (PMID 34319022, 2021). "Combination ACT with BRAF-MEK-CDK4/6i led to prolonged and deep anti-tumor responses in YOVAL1.1." (PMID 34944961, 2021). "As discussed, BRAF mutations are generally mutually exclusive with RAS mutations and this strategy would not be effective in most of the RAS mutant tumours." (PMID 34359657, 2021). "Histological features such as tumour budding, perineural invasion, apical lymph node involvement, lymph node yield, lymph node ratio, and molecular features such as MSI, KRAS, BRAF, and CDX2 may assist in prognostication and optimising adjuvant treatment." (PMID 34940086, 2021). "Given the YOVAL1.1 in vivo results, we then sought to assess whether the addition of palbociclib to combination BRAF-MEKi and pmel-1 ACT would further enhance anti-tumor activity against the BRAFi resistant SM1WT1 tumors." (PMID 34944961, 2021). "However, for the KRASG12C tumor, LINCS analysis returned different drugs (NES < −3.6, P < 0.04), inhibitors of HSP70, GSK3β, and KRAS signal transducers BRAF and RAF1." (PMID 33712615, 2021). "The clinical characteristics including age, gender, tumor location, tumor size, tumor differentiation, AJCC disease stage, KRAS/NRAS/BRAF mutation status, non-quantitative FOBT, serum CEA and CA19-9 were matched between oCRC group and yCRC group." (PMID 34799562, 2021). "In addition to tumor cells, the past decade has provided evidence that BRAFi can activate the MAPK pathway of host immune cells that express WT BRAF, thereby boosting their activity and tumor infiltration into the tumor." (PMID 33391536, 2021). "This method is reliable and clinically relevant, enabling the detection of tumor-specific mutations in CSF that direct therapy (e.g., EGFR, BRAF) even in patients with no measurable systemic disease." (PMID 34625644, 2021). "After weighing the evidence, experts recommended CT doublet plus anti-EGFR as 1L treatment for patients with RAS/BRAF WT mCRC, regardless of the primary tumor location, when cytoreduction is the goal." (PMID 34868987, 2021). "Circulating tumor DNA (ctDNA) analysis was used to identify RAS and BRAF status." (PMID 34495337, 2021). "In NSCLC mouse models, it has been found by various studies that CRaf was required for proper tumor initiation but not BRaf, as total ablation of BRaf but not CRaf allowed oncogenesis in KRas G12D and G12V mutant mice." (PMID 34680208, 2021). "The 28 tumours with BRAF mutations were enriched in CTCF binding site mutations (FDR = 5.8 × 10− 5, FC = 1.10), while 32 BRAF-wildtype tumours showed no enrichment (FDR = 0.31, FC = 1.03)." (PMID 33941236, 2021).
tumor (continued). "If the MLH1 protein is absent or if the tumor is MSI-high, further testing for methylation of the MLH1 promoter and/or the somatic BRAF p.V600E variant are recommended." (PMID 34945755, 2021). "Analyzing the whole-blood expression signature of four growth factor-related genes (ARAF, BRAF, KRAS, and RAF-1) and four genes involved in metabolism (ATP6V1H, OAZ2, PANK2, and PLD3), combined with tumor grade, they were able to predict the efficacy of PRRT with an accuracy of 95%." (PMID 33809226, 2021). "A fine needle aspiration (FNA) biopsy revealed tumor cells consistent with ATC that were positive for PD-L1, with an expression score of >95% and negative for the BRAF V600E mutation." (PMID 34123437, 2021). "Based on the observed synergy between BRAF and MYC, we surmise that distinct MYC targets may enhance KRAS-induced tumor growth via reversible immune suppression." (PMID 33674596, 2021). "Combining full-dose BRAF-inhibition with downstream MEK-inhibition (e.g., dabrafenib plus trametinib) efficiently mitigates detrimental paradoxical activation of the MAPK-pathway, which significantly decreases the incidence of secondary neoplasms." (PMID 33921947, 2021). "BRAF V600E negative tumours were significantly larger than the BRAF V600E positive (3.47 cm vs 2.31 cm respectively, P = 0.009)." (PMID 34734568, 2021). "The advent of immune checkpoint inhibitors (e.g., anti-PD-L1, anti-PD-1, anti-CTLA4) and the targeted inhibition of the MAPK pathway with BRAF and MEK inhibitors in BRAF-V600-mutant melanoma patients has led to profound and durable tumor responses in some patients with advanced melanoma." (PMID 34065877, 2021). "Besides, the whole-genome sequencing of 39 pLGGs and low-grade glioneuronal tumours showed only two novel BRAF fusion genes: BRAF-MACF1 and FXR1-BRAF." (PMID 33557011, 2021). "Although the MAPK pathway is altered in many tumor types, BRAF mutations are not very common in HNSC, including the TCGA-HNSC cohort, where only five out of 515 patients showed a BRAF alteration." (PMID 35251119, 2021). "Interestingly, while BRAF- and MEK-targeted therapy was initially developed on the basis of potent tumor-intrinsic effects, it was later discovered to have significant immune-potentiating activity." (PMID 34025662, 2021). "The dual inhibition of the BRAF/MEK and PI3K signaling pathways has been shown to substantially improve anti-tumor activity in different tumor types, essentially by inhibiting cross talks between the two pathways, which are responsible for resistance mechanisms." (PMID 34439194, 2021). "Research has shown that the site of the primary tumour influences the effectiveness of anti-epidermal growth factor receptor (EGFR) agents; we avoid the use of an anti-EGFR agent in right-sided primary tumours, even if RAS/BRAF wild type." (PMID 34440099, 2021). "Moreover, celecoxib delayed the onset of CSCC in a mouse model mediated by DMBA/TPA and of CSCC induced by the BRAF inhibitor PLX7420, reducing the tumor burden by 90%." (PMID 32331425, 2020). "While monotherapy with the BRAFi vemurafenib or the MEKi trametinib showed no anti-tumor effects in BRAF-mutant xenograft models, the combination of the MCL-1i AZD5991 with these inhibitors reduced tumor growth." (PMID 33308268, 2020).
tumor (continued). "As for clinicopathological factors, methylation phenotypes of MM did not associate with genetic mutations, such as BRAF and NRAS, age, tumor site, or the presence of ulcers." (PMID 32406600, 2020). "Multivariate regression analysis controlling for BRAF-V600E, male sex, multifocality, histology, ETE, residual tumor, T stage, N stage, M stage and AJCC stage found that only advanced N stage (P=0.038) and advanced M stage (P=0.028) were independent predictors of recurrence in the <55 age group." (PMID 31897179, 2020). "The tumor cells were robustly and diffusely positive for Trk, S100-protein, CD34, and nestin, but negative for CD56, SMA, desmin, myogenin, STAT6, EMA, CK, CD1a, CD21, CD35, CD43, WT-1(c-terminal), MelanA, HMB45, BRAF, and ALK." (PMID 32957984, 2020). "When the tumour recurred again in the brain and progression was not halted with radiation or immunotherapy, the patient was again treated with BRAF + MEK inhibitors, and a response to therapy was observed." (PMID 31857724, 2020). "This trial concluded that the combined therapy showed strong anti-tumor activity and a strong safety profile in BRAF V600E mutant NSCLC patients who have not received treatment prior to this study." (PMID 33182254, 2020). "There was a trend towards higher frequency of disease progression in target and non-target lesions in BRAF-MT patients and patients with right-sided primary tumor (BRAF-MT vs. BRAF-WT: 25.0% vs. 3.7%, right-sided vs. left-sided tumor: 18.8% vs. 8.6%)." (PMID 32449003, 2020). "In spite of the very high specificity of BRAF p.V600E for PTC, the BRAF exon 15 status of thyroid tissue surrounding the tumor is unknown." (PMID 32059434, 2020). "One patient (No 14) with tumor stage M1c had received anti-PD1 followed by BRAF inhibition with vemurafenib, and a third line combined anti-PD1 and anti-CTLA4 immunotherapy before treatment with T-VEC was induced." (PMID 32052079, 2020). "Regarding the specific tumor marker (Tg and anti-Tg) the Tg mean values ± SD in BRAF+ and BRAF– patients’ subgroups do not correlate statistically significantly: Tg 78.93 ± 142.6, respectively 74.03 ± 105.66; P = 0.93 > 0.05." (PMID 32575591, 2020). "We tested the independence of ABCG2/TOP1 status in multivariable models including tumor site, MSI status, mucinous histology, and BRAF and KRAS mutation status (without interaction terms)." (PMID 32326511, 2020). "In order to directly compare clinical utility of RT-PCR and NGS techniques for BRAF testing, we further performed an NGS panel in parallel in those patients with additional tumor material and determined the concordance between NGS and RT-PCR data of BRAF status as the reference." (PMID 36046072, 2020). "Primary tumor location (right versus left) has been shown to predict benefit from anti-epidermal growth factor receptors (EGFRs) in rat sarcoma viral oncogene homologue (RAS) and v-raf murine sarcoma viral oncogene homolog B1 (BRAF) wild-type patients." (PMID 32498251, 2020). "Previous work supports an independent role of BRAF and MEK inhibitor combination therapy in increasing tumor-infiltrating lymphocyte populations and inflammatory cytokine levels, suggesting that this effect cannot be attributed solely to exposure to the anti-PD-L1 antibody, durvalumab." (PMID 33288749, 2020). "In these cases, BRAF p.V600E was identified in three of six samples containing psammoma bodies (without viable tumor cells); in all three cases, BRAF p.V600E was also present in the PTC." (PMID 32059434, 2020). "In cUC clinical samples, the association between BRAF genotype and COX2 expression was not clear, partly because some wild-type tumours showed increased COX2 expression." (PMID 32385388, 2020).
tumor (continued). "Among the samples surrounding the PTCs, the only ones with BRAF p.V600E were those containing psammoma bodies—in the absence of identifiable tumor cells." (PMID 32059434, 2020). "MM302 was derived from a patient that was initially placed on BRAF + MEK-targeted therapy, but had an adverse reaction to the MEK inhibitor; therefore, the patient continued treatment on BRAF inhibitor alone until the tumour progressed." (PMID 31857724, 2020). "In contrast, 8/54 (15%) patients with positive VE1-immunostained CTCs lacked BRAF V600E in tumor tissues." (PMID 32695793, 2020). "Patients who received nivolumab as adjuvant therapy after tumor resection benefitted regardless of the PD-L1 or BRAF status." (PMID 32737694, 2020). "Results of the ex vivo screening indicated an apparent MAPK/PI3K signaling pathway switch in the tumor cells based on the high sensitivity of the cells to mTOR inhibition, MEK inhibition and partial response also to antifolate abitrexate, BRAF and EGFR inhibition." (PMID 32576176, 2020). "In solid tumors the main target of these drugs are oncoproteins crucial for tumor maintenance and survival such as epidermal growth factor (EGFR), B-Raf proto-oncogene/serine/threonine kinase (BRAF), proto-oncogene c-Kit (KIT), human epidermal growth factor receptor 2 (HER2)." (PMID 32218226, 2020). "Active BRAF upregulates the HMG-CoA product AcAc, which selectively enhances binding of BRAF V600E but not BRAF wild-type to MEK1 to promote activation of MEK-ERK signaling to stimulate tumor growth." (PMID 31399389, 2020). "In BRAF V600E mutant tumors, BRAFi effectively block MAPK signaling and inhibit tumor growth." (PMID 33042833, 2020). "Activation of the mutation in the mitogen-activated protein kinase (MAPK) pathway where the BRAF V600E gene is included, leads to the non-controlling tumor proliferation and thus, to the phenomenon of cell de-differentiation." (PMID 32575591, 2020). "Recent studies suggested that short-term inhibition of both BRAF and MEK in combination with anti-PD-1/L1 antibodies could enhance tumor immune infiltration, and improve tumor control in a CD8 T cells-dependent manner." (PMID 32260561, 2020). "The BRAF status of the tumor is not correlated to prognosis, whereas the TERT promoter gene mutations are." (PMID 33396957, 2020). "To date, there is no information regarding BRAF alterations in the thyroid parenchyma surrounding the tumor." (PMID 32059434, 2020). "Thus, there was a perfect correspondence between BRAF exon 15 status of the PTC and of the psammoma bodies surrounding the tumor." (PMID 32059434, 2020). "Both genetic and pharmacologic inhibition of early stage autophagy, particularly in the presence of BRAFi, reduced tumor cell growth and enhanced tumor cell death in BRAF mutant CNS tumor cells irrespective of their RAFi sensitivity." (PMID 32457939, 2020). "In our case, BRAF immunostaining was positive for only cilia cell, and the tumor itself was not stained; however, other studies reported that epithelial cells and cytoplasm had been stained." (PMID 32990811, 2020). "For AXLhi tumor cells, we previously reported that they are resistant not only to BRAF inhibition but also to inhibition of MEK or the combination." (PMID 32770055, 2020). "We successfully validated the two BRAF fusion genes, detected by a single fusion-spanning read (such as in AGAP3-BRAF), by utilizing the exact breakpoint-locations provided by NanoFG and breakpoint-spanning PCR on the non-amplified tumor DNA." (PMID 32504042, 2020). "Furthermore, activation of CD103+ DCs at the tumor site enhances tumor responses to PDL1 and BRAF inhibition." (PMID 33282290, 2020). "The location of primary tumor (left vs. right sided) and KRAS and BRAF mutation status did not significantly impact on mOS." (PMID 31615124, 2019).